BCAR4 (breast cancer anti-estrogen resistance 4)
Diseases named in the same sentence as BCAR4 in open-access papers (continued):
Sharing a sentence is not in itself a finding about the gene and the disease.
tumor (continued). "Collectively, data in the present study indicated that ELAVL1 may be downstream gene of miR-139-3p sponging to BCAR4, which are involved in tumor progressions in ESCC." (PMID 33602031, 2021). "Together, above findings indicated that silencing BCAR4 suppressed tumor growth in vivo." (PMID 29190958, 2017). "Moreover, Wnt/β-catenin signaling was downregulated in tumor tissues of nude mice derived from BCAR4-silenced HCT8 cells." (PMID 29190958, 2017). "To further examine whether BCAR4 suppressed CC tumor growth in vivo, we inoculated WT or BCAR4-silenced HCT8 cells into nude mice." (PMID 29190958, 2017). "Lapatinib, a clinically approved ERBB2/EGFR inhibitor, counteracts BCAR4-driven tumor cell growth." (PMID 26317614, 2015). "Compared with IPH-926, the original tumor specimens showed only slightly lower BCAR4 mRNA levels." (PMID 26317614, 2015). "We explored whether BCAR4 is predictive for tamoxifen resistance and prognostic for tumour aggressiveness, and studied its function." (PMID 20859285, 2010). "Patients with high BCAR4 in the tumours showed the worst MFS and overall survival." (PMID 20859285, 2010). "In addition, inhibition of BCAR4 significantly prevented tumor growth." (PMID 30962766, 2019). "In addition, in vivo tumor formation assay showed BCAR4 inhibition could effectively restricted in vivo tumor growth." (PMID 30962766, 2019). "As a prognostic marker, BCAR4 could predict tamoxifen resistance and tumor invasion." (PMID 27732939, 2017). "Hence, BCAR4 mRNA in the tumor has been maintained in the derived BC cell line." (PMID 26317614, 2015). "However, it remains to be established whether BCAR4-positive primary tumours have elevated levels of phosphorylated ERBB2 or ERBB3." (PMID 20859285, 2010). "BCAR4 may have clinical relevance for tumour aggressiveness and tamoxifen resistance." (PMID 20859285, 2010). "Some lncRNAs, including 91 H, BCAR4 and MALAT-1, are overexpressed, exhibiting oncogenic features, whereas others like Loc285194 and MEG3 are downregulated and serve tumor suppressive roles." (PMID 40868849, 2025). "LncRNAs known to be a regulatory factor of tumor stem cells included GAS5, NEAT1, SOX2OT, Malat-1, HOTAIR, PVT1, BCAR4 and RBM5-AS1." (PMID 31143372, 2019). "Among the 6 studies that reported lncRNAs function as tumor oncogenes and used tumor weight as the major outcome measure, 5 different lncRNAs (HOTAIR, TUG1, BCAR4, MALAT1 and FGFR3-AS1) were reported." (PMID 29245999, 2017). "Therefore, we investigated whether BCAR4 mRNA levels give information on tumour aggressiveness." (PMID 20859285, 2010). "For example, BCAR4, THOR, and LINC00942 participate in the positive regulation of invasion and metastasis of GC platinum-resistant cell lines by promoting the activation of tumor stem cells." (PMID 38927012, 2024). "Furthermore, the mRNA level of BCAR4 in 32 paired of tumor and tumor-adjacent tissues isolated from ESCC patients were recorded, and found that BCAR4 was visibly enhanced in ESCC tissues when compared with the adjacent tissues." (PMID 33602031, 2021). "The pooled results from 5 studies indicated that the high lncRNA BCAR4 expression was not related to tumor size (OR 1.70, 95% CI: 0.88–3.28; P < .001, I2 = 68%)." (PMID 31124974, 2019). "However, only nine studies were included without extensively searching other databases or providing information regarding BCAR4 and other clinical parameters, such as PFS, tumor size, gender and age." (PMID 31762809, 2019). "To rule out that BCAR4 expression in BC cell lines is an artifact due to in vitro cultivation, we analyzed the original clinical tumor specimens corresponding to IPH-926 cells." (PMID 26317614, 2015). "No relation between categorised BCAR4 mRNA levels and age, menopausal status, tumour size, or tumour grade was found." (PMID 20859285, 2010).
tumor (continued). "No relation between categorised BCAR4 mRNA levels and age, menopausal status, tumour size, nodal status, or adjuvant systemic treatment of the patients was observed." (PMID 20859285, 2010). "If BCAR4-positive tumours are driven by ERBB2 signalling, in the absence of gene amplification or overexpression, as our results suggest, then more patients may benefit from ERBB2-directed therapy." (PMID 20859285, 2010).
BCAR4 also shares sentences with these, for which no sentence is quoted: prostate carcinoma (3 papers); digestive system cancer (2); esophageal cancer (2); brain cancer (1); breast (1); cervical squamous cell carcinoma (1); endocervical adenocarcinoma (1); infection (1); lung squamous cell carcinoma (1); prostate adenocarcinoma (1); sarcoma (1); triple-negative breast carcinoma (1).